ENSG00000264668 (novel protein)
Gene: Protein-coding gene on chromosome 8 (143,247,110 to 143,276,403, forward strand). Ensembl gene ENSG00000264668.
Genetic constraint (gnomAD): Loss-of-function variants: 7 observed, 6.94 expected, observed/expected ratio (o/e) 1.01, 90% interval 0.57 to 1.75. That is too few expected variants to judge how well the gene tolerates losing a copy. Missense variants: 302 observed, 273.7 expected, observed/expected ratio (o/e) 1.1, 90% interval 1 to 1.21. Synonymous variants: 123 observed, 105.56 expected, observed/expected ratio (o/e) 1.17, 90% interval 1.01 to 1.35.